KPNA3 (karyopherin subunit alpha 3)
Description:
Functions in nuclear protein import as an adapter protein for nuclear receptor KPNB1. Binds specifically and directly to substrates containing either a simple or bipartite NLS motif. Docking of the importin/substrate complex to the nuclear pore complex (NPC) is mediated by KPNB1 through binding to nucleoporin FxFG repeats and the complex is subsequently translocated through the pore by an energy requiring, Ran-dependent mechanism. At the nucleoplasmic side of the NPC, Ran binds to importin-beta and the three components separate and importin-alpha and -beta are re-exported from the nucleus to the cytoplasm where GTP hydrolysis releases Ran from importin. The directionality of nuclear import is thought to be conferred by an asymmetric distribution of the GTP- and GDP-bound forms of Ran between the cytoplasm and nucleus. In vitro, mediates the nuclear import of human cytomegalovirus UL84 by recognizing a non-classical NLS. Recognizes NLSs of influenza A virus nucleoprotein probably through ARM repeats 7-9.
Synonyms: SRP1gamma; SRP4; hSRP1; IPOA4; SPG88; SRP1
Tractability: PROTAC: ubiquitination databases record sites on it; its protein half-life has been measured.
Gene: Protein-coding gene on chromosome 13 (49,697,744 to 49,793,068, reverse strand). Ensembl gene ENSG00000102753.
Subcellular location: Cytoplasm; Nucleus
Subcellular location (Human Protein Atlas): Nucleoplasm; Cytosol
Pathways (Reactome):
Disease: Maturation of DENV proteins; NS1 Mediated Effects on Host Pathways
Immune System: ISG15 antiviral mechanism
Gene Ontology:
Molecular function: protein binding; nucleocytoplasmic carrier activity; nuclear import signal receptor activity
Biological process: NLS-bearing protein import into nucleus; protein-containing complex assembly; protein import into nucleus
Cellular component: NLS-dependent protein nuclear import complex; nucleoplasm; nucleus; cytosol; nuclear pore; cytoplasm
Genetic constraint (gnomAD): Loss-of-function variants: 2 observed, 29.45 expected, observed/expected ratio (o/e) 0.0679, 90% interval 0.027 to 0.21. The upper end of that interval is the gene's LOEUF score, 0.21, which puts it in group 1 of 6, group 1 being the genes least tolerant of losing a copy. Missense variants: 169 observed, 326.97 expected, observed/expected ratio (o/e) 0.52, 90% interval 0.46 to 0.59. Synonymous variants: 103 observed, 113.75 expected, observed/expected ratio (o/e) 0.91, 90% interval 0.77 to 1.07.
Homologues: Orthologues: chimpanzee KPNA3 (100% identical), macaque KPNA3 (99% identical), dog KPNA3 (99% identical), mouse Kpna3 (99% identical), pig KPNA3 (99% identical), rat Kpna3 (99% identical), guinea pig KPNA3 (98% identical), rabbit KPNA3 (96% identical), tropical clawed frog kpna3 (95% identical), zebrafish kpna3 (95% identical), Drosophila melanogaster Kap-alpha3 (68% identical), Caenorhabditis elegans ima-3 (62% identical), and 1 more. Paralogues in human: KPNA4 (86% identical), KPNA2 (51% identical), KPNA5 (48% identical), KPNA6 (47% identical), KPNA1 (46% identical), KPNA7 (42% identical).
Diseases named in the same sentence as KPNA3 in open-access papers:
KPNA3 is named in the same sentence as 26 diseases in open-access papers, as found by Europe PMC text mining. Sharing a sentence is not in itself a finding about the gene and the disease. The quoted sentences say what the papers report.
colorectal cancer (12 papers, 2018 to 2024). A primary or metastatic malignant neoplasm that affects the colon or rectum. "This SMARCA1-NURF complex is also recruited by another lncRNA, lnc-DLEU1, to the KPNA3 promoter in colorectal cancer, where it initiates KPNA3 expression via H3K27ac enrichment and promotes tumor cell proliferation and migration." (PMID 37175555, 2023). "DLEU1 recruits SMARCA1 to epigenetically activate the KPNA3 gene in colorectal cancer, thereby promoting cell proliferation and migration." (PMID 35619131, 2022). "LncRNA DLEU1 recruits SMARCA1 to the KPNA3 promoter and activates its transcription, thereby promoting the proliferation and migration of colorectal cancer." (PMID 32661324, 2020). "Collectively, DLEU1 recruited SMARCA1 to epigenetically activate downstream gene KPNA3, thereby promoting proliferation and migration in colorectal cancer." (PMID 30098595, 2018). "In colorectal cancer tissues, by activating KPNA3 via recruiting SMARCA1, an essential subunit of the NURF chromatin remodelling complex, increased expression of DLEU1 was observed, and higher expression of DLEU1 in patients indicated lower survival rate and a poorer prognosis." (PMID 32742772, 2020). "In colorectal cancer, the SMARCA1-NURF complex is recruited by lnc-DLEU1 to the KPNA3 promoter and initiates KPNA3 expression via H3K27ac enrichment, which promotes tumor cell proliferation and migration." (PMID 34736517, 2021). "For instance, DLEU1 is upregulated in colorectal cancer (CRC) and recruits SMARCA1 to epigenetically activate a downstream target gene, KPNA3, which leads to CRC progression." (PMID 34650128, 2021).
schizophrenia (3 papers, 2012 to 2022). A major psychotic disorder characterized by abnormalities in the perception or expression of reality. "Evidence from human studies has indicated that single nucleotide polymorphisms (SNP) in the KPNA3 gene are associated with the occurrence of several psychiatric disorders accompanied by abnormal reward-related behavior, including schizophrenia, major depression, and substance addiction." (PMID 35844217, 2022). "Interestingly, independent studies have identified single nucleotide polymorphisms (SNPs) of KPNA3, predicted to decrease KPNA3 expression, to be associated with schizophrenia in cohorts from the United Kingdom, China, and Australia." (PMID 35844217, 2022). "Finally, the KPNA3 gene at the 13q14.3 locus, has also been implicated as a potential schizophrenia susceptibility gene." (PMID 23825557, 2013). "Multiple genes encoded by chromosome 13 have been suggested to contribute to schizophrenia susceptibility, including DAOA, 5-HTR2A, KPNA3 and KPNB3, ESD, ATXN8OS, KFL5, EFNB2, and PCDH8." (PMID 22214315, 2012).
hereditary spastic paraplegia (2 papers, 2025). Hereditary spastic paraplegias (HSP) comprise a genetically and clinically heterogeneous group of neurodegenerative disorders characterized by progressive spasticity and hyperreflexia of the lower limbs. "Notably, it has been recently revealed that dominant KPNA3 mutations cause infantile-onset hereditary spastic paraplegia in humans." (PMID 39621428, 2025). "Several studies in patients with hereditary spastic paraplegia (HSP), a neurodegenerative disease of the upper motoneuron, have found various missense mutations in the KPNA3 gene, suggesting an underlying defect in nucleocytoplasmic import or a compromised axonal transport." (PMID 40565582, 2025).
Alzheimer disease (1 paper, 2021). A progressive, neurodegenerative disease characterized by loss of function and death of nerve cells in several areas of the brain leading to loss of cognitive function such as memory and language. "Abnormally upregulated levels of KPNA3 found in cDNA microarray studies of Alzheimer’s disease human brains." (PMID 34019093, 2021).
breast carcinoma (1 paper, 2025).
COVID-19 (1 paper, 2021). A disease caused by infection with severe acute respiratory syndrome coronavirus 2. "COVID-19 patients showed alterations in KPNA3, KPNA5, KPNA7, KPNB1, RHOA, and CDC42 expression compared with non-COVID-19 patients." (PMID 34696514, 2021). "Decrease in KPNA3 (p = 0.0526) and increase in KPNB1 (p = 0.054) expressions were found with marginal significance in COVID-19 patients (I.I)." (PMID 34696514, 2021).
dysferlinopathy (1 paper, 2022). "In both datasets, MVP, GRN, and ERP29 showed significantly higher expression levels, while RNF128, NFYB, and KPNA3 had significantly lower expression levels in dysferlinopathy than normal controls." (PMID 36203997, 2022). "Consistent with the two datasets, MVP, GRN, and ERP29 expression were significantly upregulated, and RNF128, NFYB, and KPNA3 were significantly downregulated in the dysferlinopathy patients compared with the controls." (PMID 36203997, 2022). "A downregulation of KPNA3 expression in dysferlinopathy may exacerbate the disease by terminating the heat shock response." (PMID 36203997, 2022).
hepatocellular carcinoma (1 paper, 2020). A malignant tumor that arises from hepatocytes. "More recently, KPNA3 has been identified to contribute to sorafenib resistance by inducing epithelial-mesenchymal transition in hepatocellular cancer." (PMID 33585440, 2020). "KPNA3 is demonstrated to be capable of promoting the growth and invasiveness of hepatocellular carcinoma cells." (PMID 33585440, 2020).
major depression (1 paper, 2022). "Furthermore, in the Australian cohort, KPNA3 SNPs were additionally associated with a wide range of other psychiatric disorders, including alcoholism, opioid addiction, and major depression." (PMID 35844217, 2022).
motor neuron degeneration (1 paper, 2025). "A comparable study has not been performed so far and regarding the currently established association of KPNA3 and MND, it should clarify, if a total absence of KPNA3 (or KPNA4) would be sufficient to develop symptoms of motor neuron degeneration." (PMID 40565582, 2025).
motor neuron diseases (1 paper, 2025). "Although much less evidence exists for an impact of the closely related paralogue KPNA4 on the development of motor neuron diseases (MND), we decided to analyse Kpna4-knockout (KO) mice in parallel, as KPNA3 and KPNA4 display a high homology and share common cargoes." (PMID 40565582, 2025).
Salmonella Infections (1 paper, 2025). Infections with bacteria of the genus SALMONELLA. "Another one is KPNA3, which is associated with nuclear protein import and plays a role in Salmonella infection processes." (PMID 40003092, 2025).
Spinocerebellar ataxia type 3 (1 paper, 2025). "Indeed, KPNA3-dependent nuclear localization of ataxin-3 acts as a key event in the pathogenesis of spinocerebellar ataxia type 3, while ablation of KPNA3 in mice results in abnormal sperm morphology and influences male fertility." (PMID 39621428, 2025).
cancer (8 papers, 2014 to 2025). A tumor composed of atypical neoplastic, often pleomorphic cells that invade other tissues. "lncRNA DLEU1 can inhibit CRC cell growth, motility, and invasion, indicating the relevance of the DLEU1/SMARCA1/KPNA3 axis in the etiology of this cancer type." (PMID 37280524, 2023). "DLEU1 activates KPNA3, which is related to the increased proliferation and migration of cancer cells." (PMID 33735310, 2021). "The lncRNAs DLEU1 and DLEU2 at 13q14.3 are often deleted in multiple types of cancers, and DLEU1 and DLEU2 modulate nuclear factor B function by down-regulating the transcription of their neighboring protein-coding KPNA3 and the microRNAs miR-15 and miR-16." (PMID 24586304, 2014).
tumor (8 papers, 2018 to 2025). "Kruskal–Wallis test analysis showed that the levels of HOTTIP and KPNA3 in the tumor tissues of patients with recurrent CRC who received mitomycin treatment were higher than those in tumor tissues of patients with primary CRC." (PMID 33585440, 2020). "In our study, we found that the expression of KPNA3 was significantly up-regulated in CRC tissues compared to non-tumor tissues." (PMID 30098595, 2018). "To further examine whether DLEU1 regulated CRC development and progression by activating KPNA3, we analyzed the expression of KPNA3 in CRC tissues and non-tumor tissues." (PMID 30098595, 2018). "KPNA3 was also up-regulated in the 100 CRC samples compared to non-tumor tissues." (PMID 30098595, 2018).
infection (4 papers, 2018 to 2025). The state of being infected such as from the introduction of a foreign agent such as serum, vaccine, antigenic substance or organism. "Considering that the infection of FAdV-4 causes a significant decrease of colloid osmotic pressure, it is not difficult to speculate that the interaction between Fiber-2 of FAdV-4 with KPNA3/4 might be related with hydropericardium symptom." (PMID 33616472, 2021). "In enterovirus (EMCV) infection, DDX56 directly binds KPNA3/KPNA4, which are critical nuclear import receptors." (PMID 41217109, 2025). "In the context of infection, MERS-CoV 4b protein also preferentially bound to KPNA4 over all other karyopherins, including KPNA3." (PMID 29370303, 2018). "In addition, the expression levels of KPNB1, KPNA1, KPNA2, KPNA4, KPNA6, and KPNA7 changed with the infection time of the three strains while KPNA3 and KPNA5 did not change with the incubation time." (PMID 40687856, 2025).
psychiatric disorder (2 papers, 2013 to 2022). A disorder characterized by behavioral and/or psychological abnormalities, often accompanied by physical symptoms. "Here, for the first time, we examined potential abnormalities in reward-related behavior as a result of KPNA3 deficiency, which had previously been genetically implicated in the etiology of several psychiatric disorders in humans." (PMID 35844217, 2022). "Such insights suggest KPNA3 to be a possible genetic risk factor for psychiatric disorders; however, the causal relationship between KPNA3 and such disorders is still unknown." (PMID 35844217, 2022). "Further investigation will be required to ascertain the relevance of KPNA3 to these two related psychiatric disorders." (PMID 23825557, 2013).
inflammatory myopathies (1 paper, 2022). "In inflammatory myopathies, GRN, MVP and NFYB showed high diagnostic value, while RNF128, ERP29 and KPNA3 showed poor diagnostic value, indicating high inflammation activation but little involvement of protein homeostasis." (PMID 36203997, 2022).
neurodegenerative disease (1 paper, 2022). A disorder of the central nervous system characterized by gradual and progressive loss of neural tissue and neurologic function. "Abundant KPNA3 and KPNA4 isoforms play important roles in neuronal cell physiology and their dysregulation was linked to neurodegenerative diseases." (PMID 35927988, 2022). "KPNA3 and KPNA4 were also studied regarding the transport of TAR DNA-binding protein 43 (TDP-43) and the formation of aggregates of this protein in the central nervous system, which is a hallmark of many neurodegenerative diseases." (PMID 35927988, 2022).
KPNA3 also shares sentences with these, for which no sentence is quoted: attention deficit-hyperactivity disorder (1 paper); colorectal tumor (1); dysplasia (1); endometrial cancer (1); Hodgkins lymphoma (1); leukemia (1); ovarian carcinoma (1).